OR4N4C (olfactory receptor family 4 subfamily N member 4C)
Description:
Odorant receptor.
Gene: Protein-coding gene on chromosome 15 (21,651,844 to 21,652,968, forward strand). Ensembl gene ENSG00000279408.
Subcellular location: Membrane
Subcellular location (Human Protein Atlas): Centrosome
Gene Ontology:
Molecular function: olfactory receptor activity; G protein-coupled receptor activity
Biological process: detection of chemical stimulus involved in sensory perception of smell; G protein-coupled receptor signaling pathway
Cellular component: plasma membrane; membrane
Homologues: Orthologues: macaque OR4N4 (94% identical), dog OR4N2B (85% identical), mouse Or4n4 (83% identical), rat Or4n4 (82% identical), mouse Or4n4b (80% identical), rat Or4n4 (80% identical). Paralogues in human: OR4N4 (99% identical), OR4N2 (83% identical), OR4N5 (82% identical), OR4M1 (53% identical), OR4M2 (52% identical), OR4M2B (51% identical), OR4D5 (49% identical), OR4E2 (47% identical), OR4Q3 (47% identical), OR4D1 (47% identical), OR4D11 (47% identical), OR4D2 (47% identical), and 116 more.